LCN2 (lipocalin 2)
Diseases named in the same sentence as LCN2 in open-access papers (continued):
Sharing a sentence is not in itself a finding about the gene and the disease.
Sepsis (continued). "For example, in the sepsis model of LCN2‐deficient mice, intracellular labile iron was elevated." (PMID 36974345, 2023). "Therefore, the bactericidal activity of LCN2-deficient immune cells is attenuated, and LCN2-gene knockout mice are prone to infection and sepsis." (PMID 34359830, 2021). "Lipocalin 2 has been shown to be useful for the early diagnosis, risk stratification and prognosis of sepsis in the emergency department, as well as for the detection of multiorgan dysfunction and mortality in patients with sepsis and septic shock." (PMID 34200950, 2021). "Lcn-2 expression was positively associated with post-surgical development of sepsis." (PMID 33065981, 2020). "Moreover, the associated systemic inflammatory cascade upon sepsis-induction additionally fosters the expression of Lcn-2 as first-line response of the innate immune system." (PMID 33065981, 2020). "In fact, Lcn2 deficient mice are more prone to infections and sepsis." (PMID 31091692, 2019). "The data indicated that high expression of miR-122-5p, OLFM4, and LCN2 was associated with a low 28-day survival rate in septic patients with poor prognosis, further suggesting that these miRNAs and proteins in EVs have potential in the diagnosis and prognosis of sepsis." (PMID 39901167, 2025). "Interleukin 7 and lipocalin 2-related interactions between bone metabolism and the immune system could partially explain the association of osteoporosis with an increased risk of infections and sepsis." (PMID 37384614, 2023). "In addition to a strong inflammatory response, LCN2 levels may have been affected by the kidney injury associated with bloodstream infection, including sepsis, in the present study." (PMID 37932342, 2023). "Compared with those in healthy controls, the levels of CD177, SLPI, OLFM4, and LCN2 were elevated in plasma-EVs from patients with sepsis." (PMID 39901167, 2025). "The change of LCN2 and ferritin has been widely reported in sepsis patients and has become a key indicator for predicting 28‐day mortality in patients with CAP or sepsis." (PMID 40501500, 2025). "Downregulation of LCN2 alleviated neuronal damage and significantly improved synaptic and cognitive impairments in sepsis mice." (PMID 40025014, 2025). "Bioinformatics and western blot analyses demonstrated a significant increase in Lipocalin-2 (LCN2) during sepsis as a key hub gene involved in immune and neurological inflammation." (PMID 40025014, 2025). "In the COMBAT study LCN2 was one of the main genes separating COVID-19 severity groups of patients from sepsis." (PMID 40240424, 2025). "Meanwhile, the levels of LCN2 in learning and memory-related hippocampus are markedly increased during sepsis." (PMID 40025014, 2025). "In part, the long non-coding RNA Lcn2-204 is responsible for ferroptosis in cardiomyocytes in sepsis." (PMID 39372215, 2024). "Based on a machine learning approach, LCN2 is considered as biomarker for sepsis-induced acute respiratory distress syndrome." (PMID 39372215, 2024). "In the present study, we reveal the protective role of LCN2 in SILI in CLP model of sepsis by attenuating PTGS2-dependent ferroptosis." (PMID 39512683, 2024). "Our findings revealed a significant increase in LCN2 expression in both sepsis-induced liver tissues and hepatocytes treated with LPS." (PMID 39512683, 2024). "In a lipopolysaccharide (LPS)-induced sepsis model, LCN2 knockout exacerbates inflammation, oxidative stress, organ damage by regulating iron homeostasis." (PMID 39512683, 2024). "In the model of LPS-induced sepsis, LCN2-/- mice showed higher oxidative products in the liver compared with WT mice." (PMID 38704585, 2024). "Among the iron metabolism indicators, LCN2 was significantly higher in sepsis at D1 and D3 (p < 0.01 and p = 0.03, respectively)." (PMID 37932342, 2023). "After sepsis, LCN2 was predominantly decreased in lung fibroblasts among KO mice and the same results as detected by immunofluorescence." (PMID 38093296, 2023).
Sepsis (continued). "Similar with LCN2, LTF is also an iron-binding and multifunctional protein among the sepsis associated iron metabolism-related genes identified in this study." (PMID 36820206, 2023). "The LCN2 knockout mice also showed a protective role in sepsis, as organ damage and mortality were worse in LCN2 knockout mice than in wild-type mice after LPS injection." (PMID 37932342, 2023). "Our results showed that genes such as IFN-γ, TNF-α, IL-6, MIP-2, IL-10, KC (CXCL1), CCL-2, MPO, MMP9, TLR2, and LCN2 were significantly upregulated in the lungs of sepsis-induced ARDS mice compared to control mice." (PMID 37822934, 2023). "To explore if Lcn2 was induced in adipocyte precursors following sepsis condition, we subclusterized fibroblasts and a significant increase of Lcn2 expression was detected in fibroblast adipocyte precursors (FAP)." (PMID 37517520, 2023). "LPS-stimulated Lcn2-/- mice also exhibit elevated hallmarks of sepsis, including the expression of proinflammatory cytokines such as TNF-α and IL-18, immune cell apoptosis, and systemic organ dysfunction." (PMID 36054235, 2022). "LCN2 was widely distributed in the liver, lung, kidney, and other organs as an acute inflammatory protein in sepsis mice." (PMID 35990970, 2022). "In current study, the level of LCN-2 was much higher in plasma in severe sepsis patients which is similar to previous reports." (PMID 36419491, 2022). "Altogether these findings parallel the observation of increased expression of Lcn2 during infection, elevated serum LCN2 during sepsis, and further support a possible role for LCN2 in the innate immune response to A. baumannii." (PMID 36054235, 2022). "Regarded as a biomarker of infected diseases, LCN2 offers protection against E. coli-induced septicemia, pneumonia, and urinary tract infection." (PMID 35990970, 2022). "Three specific granule genes (OLFM4, LTF, and LCN2) showed <2-fold differences in SIRS vs. presurgical but >10-fold higher levels in sepsis vs. both SIRS and presurgical." (PMID 35844509, 2022). "High plasma LCN2 also predicted high mortality and cardiac dysfunction in severe sepsis and septic shock patients." (PMID 35990970, 2022). "This notion is exemplified in a study published at the time this manuscript was in preparation, demonstrating that administration of recombinant LCN2 provides partial protection from mortality of neutropenic mice infected with A. baumannii sepsis." (PMID 36054235, 2022). "Along these lines, we recently showed that renal tubular cells secrete iron-free Lcn-2 upon sepsis-induced damage, whereby Lcn-2 serves as a marker of renal injury." (PMID 34069743, 2021). "In a LPS-induced sepsis model, Lcn2 knockout mice showed a dysregulated iron metabolism that resulted in an increased apoptosis of leukocytes, an increased release of pro-inflammatory cytokines and a higher mortality." (PMID 34712224, 2021). "Elevated Lcn2 (also referred to as NGAL) in sepsis patients was found to be related to cardiac injury and positively correlated with BNP levels." (PMID 34121925, 2021). "In models of LPS-induced sepsis or retinal degeneration, recent reports have shown that lipocalin-2 can serve as a potent neuroprotective factor in response to neuro-inflammation." (PMID 34108554, 2021). "Differently expressed microRNAs were then validated by quantitative reverse transcriptase polymerase chain reaction in 52 sepsis-alone and 34 sepsis-induced coagulopathy patients; plasma lipocalin-2 was measured as well." (PMID 32075600, 2020). "Although the MΦ phenotype is playing a crucial role during the development of sepsis-induced renal injury and Lcn-2 appears as a critical MΦ phenotype determinant, the effect of MΦ-derived Lcn-2 has so far not been addressed in a CLP-induced sepsis model." (PMID 33065981, 2020). "Further prospective follow‐up studies with serial sampling should validate the potential role of MR‐ProADM and lipocalin 2 in predicting clinical worsening of patients with infection or sepsis." (PMID 32073224, 2020).
Sepsis (continued). "Mid‐regional proadrenomedullin and lipocalin 2 are the most representative biomarkers of sepsis and septic shock respectively." (PMID 32073224, 2020). "Considering the importance of microglia-astrocyte crosstalk in rodent and human neural cells, we measured LCN2 abundance in human neural cells in response to LPS, a prototypical pro-inflammagen whose levels are exacerbated in endotoxemia and sepsis." (PMID 33171886, 2020). "Lcn2 can combat gut-origin sepsis via maintaining homeostasis of the microbiota to alleviate gut barrier injury." (PMID 33204219, 2020). "Lcn2 should be considered for the treatment of neutropenic sepsis and gastrointestinal damage during chemotherapy to prevent or minimize the adverse effects of cancer chemotherapy." (PMID 32365611, 2020). "Taking into account that Lcn-2 binds and transports iron with high affinity, we aimed at clarifying if Lcn-2 fulfills different biological functions according to its iron-loading status and its cellular source during sepsis-induced kidney failure." (PMID 33065981, 2020). "Lcn2-/- mice are prone to infection and sepsis, suggesting that this pleotropic innate immune molecule promotes host resistance against infection." (PMID 32365611, 2020). "Since Lcn-2 is a good biomarker for ischemic or nephrotoxic renal damage, we aimed at identifying its role during the course of sepsis." (PMID 33065981, 2020). "Lcn-2 protein in serum was rapidly up-regulated at 6 h after sepsis induction and subsequently increased up to 48 h." (PMID 33065981, 2020). "Collectively, inducible intra- and extra-gut expressions of Lcn2 by infection- and inflammation-related molecules suggest that Lcn2 plays important roles in gut-origin sepsis." (PMID 31375129, 2019). "The aim of the present review is to provide new insights into the possible roles of Lcn2 in gut-origin sepsis and to pave the way for developing treatment strategies targeting Lcn2 for sepsis." (PMID 31375129, 2019). "Elevated levels of Lcn2 protein in the plasma after bacterial infection has been described in animal models as well as in critically ill patients, indicating the potential functions and/or roles of Lcn2 in the pathogenesis of sepsis." (PMID 31375129, 2019). "In this narrative review, we provide a comprehensive description based on currently available evidence of the clinical implications of Lcn2 and its therapeutic potency in gut-origin sepsis." (PMID 31375129, 2019). "In the field of intestinal inflammation and critical illnesses, Lcn2 appears to be of clinical relevance in gut-origin sepsis." (PMID 31375129, 2019). "Impaired/delayed liver regeneration in Lcn2-null mice after partial hepatectomy, Lcn2-inhibited renal apoptosis during peritonitis-induced sepsis, and Lcn2-enhanced reparative tubule formation in vitro have also been documented." (PMID 31375129, 2019). "It is noteworthy that in spite of the contradiction to its foregoing pro-apoptotic effects on myeloid cells, the jury is still out since the apoptosis-related role of Lcn2 is seldom examined in the context of sepsis." (PMID 31375129, 2019). "Elevated expression levels of both Lcn2 gene and protein in the hepatocytes, and release of Lcn2 protein into the systemic circulation, were detected in a mouse model of sepsis." (PMID 31375129, 2019). "This direct dose-dependent extracellular bacteriostatic function of Lcn2 against E. coli, one of the major pathogens of gut-origin sepsis, has also been shown by other groups in in vitro experiments." (PMID 31375129, 2019). "Lcn2, an antimicrobial protein, protects endotoxin-induced sepsis and diet-induced insulin resistance." (PMID 26219821, 2015). "Comparison of DEGC to another published experimental sepsis study yielded, e.g., the significantly upregulated LCN2 gene in the murine CLP model, whose protein mediating an innate immune response by sequestering iron." (PMID 23024636, 2012). "We also measured the concentrations of IL-6 and LCN2, establishing serum markers of sepsis." (PMID 40230851, 2025).
Sepsis (continued). "However, a decrease in neutrophils and macrophages, along with elevated serum LCN2, predicts a potentially higher 28‐day mortality in sepsis patients." (PMID 40501500, 2025). "In addition, the levels of OLFM4 and LCN2 were greater in patients with septic shock than in those with sepsis." (PMID 39901167, 2025). "Inhibition of LCN2 could be therapeutically beneficial in treating sepsis-induced synaptic and cognitive impairments." (PMID 40025014, 2025). "Further investigation revealed that independent prognostic factors for 28-day overall survival in patients with sepsis included LCN2 (OR = 1.326, 95% CI 1.019–1.726, P = 0.036), OLFM4 (OR = 1.002, 95% CI 1.000-1.005, P = 0.023), and miR-122-5p (OR = 1.625, 95% CI 1.137–2.322, P = 0.008)." (PMID 39901167, 2025). "Collectively, these findings suggest that LPS may contribute to sepsis-related cognitive impairments through the significant upregulation of glia-released LCN2." (PMID 40025014, 2025). "Given the deteriorative effects of LCN2 in SAE, downregulation of LCN2 might be a potential strategy for the treatment of sepsis-associated cognitive dysfunction." (PMID 40025014, 2025). "The top ten differentially expressed genes in this study include Gm29879, Lcn2, Cxcl10, Zbp1, Lbhd2, C5aR1, Cxcl10, Lbhd2, Cxcl9, and Fpr1, all of which might play a role in the pathophysiology of sepsis-induced WMI." (PMID 41584453, 2025). "A number of studies have found that LCN-2 expression is upregulated in sepsis." (PMID 38912048, 2024). "Notably, we identified five key genes (LTF, LCN2, ELANE, MPO, CEACAM8) associated with sepsis using the intersections of the top genes identified by cytoHubba and greenyellow module genes of the WGCNA." (PMID 38912048, 2024). "This study suggests a critical role of LTF, LCN2, ELANE, MPO and CEACAM8 in sepsis and may provide potential diagnostic biomarkers and therapeutic targets for the treatment of sepsis." (PMID 38912048, 2024). "Moreover, in in vitro sepsis model, LCN2 overexpression notably ameliorated LPS-induced cell injury, oxidative stress, and ferroptosis by inhibiting PTGS2 expression." (PMID 39512683, 2024). "In addition, LCN2 levels were increased in patients with sepsis and other infections and in patients with different inflammatory diseases." (PMID 39403549, 2024). "Therefore, the present results suggest an important action of LCN2 in sepsis pathogenesis, warranting further study." (PMID 37932342, 2023). "Acute LCN2 levels were significantly higher in patients with sepsis (p < 0.01)." (PMID 37932342, 2023). "LCN2 deficiency dysregulates the host iron homeostasis and exacerbates endotoxin-induced sepsis, therefore development of a therapeutic strategy targeting lipocalin-2 could be highly promising in the management of gut-origin sepsis." (PMID 36820206, 2023). "Among them, lipocalin 2 was found to have the highest diagnostic value as its expression showed significant differences in all the comparisons including sepsis vs healthy controls, sepsis vs non-sepsis diseases, and mild forms vs severe forms of sepsis." (PMID 36820206, 2023). "Lipocalin-2 (LCN-2) is a key regulator of lipid metabolism which has been recently proved closely related to sepsis, however, the relationship between LCN-2 and septic myocardial injury remains unknown." (PMID 36419491, 2022). "In the heart, some reports also indicated that LCN2 was significantly expressed during in vivo and in vitro experiments on cardiac hypertrophy and heart failure, and high plasma LCN2 was correlated with high mortality and myocardial dysfunction in severe sepsis." (PMID 36911241, 2022). "In this study, we focus on the acute-phase of sepsis-induced myocardial injury where the role of LCN-2 remains unclear, and found a strong relationship with myocardial damage based on clinical and laboratory evidence." (PMID 36419491, 2022). "Furthermore, neutrophil gelatinase-associated lipocalin (NGAL, lipocalin-2) was used as biomarker for sepsis-induced AKI." (PMID 33996970, 2021).